IL4 (interleukin 4)
Diseases named in the same sentence as IL4 in open-access papers (continued):
Sharing a sentence is not in itself a finding about the gene and the disease.
tumor (continued). "The therapeutic blockade of IL-4/IL-13 could, therefore, yield opposing outcomes, depending on tumor type and stage." (PMID 40981274, 2025). "Neutralization of IL-4 and IL-5 results in increased tumor load and impaired clearance." (PMID 39962262, 2025). "Hence, using CaMKK2 inhibitors would selectively modulate macrophage fate in stiff tissues, whereas the IL‐4‐induced macrophage polarization in non‐tumor tissues would remain unaffected." (PMID 40036145, 2025). "FL/GM-DCs achieved significantly better tumor control compared with GM/IL4-DCs." (PMID 40977690, 2025). "Additionally, these exosomes stimulate HCC cells to release pro-tumor cytokines like GM-CSF, VEGF, and IL-4, which amplify M2 macrophage recruitment and polarization, creating a self-reinforcing cycle that supports tumor progression." (PMID 40764998, 2025). "In addition to shaping macrophage function, IL-4 directly impairs anti-tumor immunity by inhibiting T cell effector functions." (PMID 40948749, 2025). "We hypothesize that BV2 may have a similar function to IL‐4‐treated BMDMs to limit ALTS1C1 tumor cell proliferation." (PMID 40747560, 2025). "Within the tumor microenvironment, M2 cytokines, including IL-4, IL-13, and IL-10, are present, and TAMs in various cancer models exhibit an M2 activation profile characterized by increased expression of CD163, MRC-1, C-type lectins, IL-10, and Arg-1, as well as reduced production of IL-12." (PMID 40544275, 2025). "In the Raji lymphoma model, pairing Fc–IL‐4 with CD19‐CAR‐T therapy led to 75% tumour clearance." (PMID 39739593, 2025). "Similarly, tumor-associated IL-4 directs CD8+ T-cells to adopt a “type 2” phenotype, impairing their anti-tumor functionality." (PMID 40507238, 2025). "In patients affected by BCC, a more indolent and less aggressive form of skin cancer, tumor-infiltrating lymphocytes (TILs) express both type 1, i.e., IL-2 and IFNγ, and type 2, i.e., IL-4 and IL-10 cytokines, with the former mainly produced by TILs and the latter by adherent, TIL-depleted cells." (PMID 40868818, 2025). "IL-4 and related Type 2 cytokines are thought to drive tumor growth and immune evasion in MF." (PMID 40864740, 2025). "For example, stimulation of macrophages in vitro with LPS ± IFNg to derive an inflammatory, anti-tumor M1 phenotype results in induction of glycolysis, whereas stimulation with IL-4 to generate an immunosuppressive, pro-tumorigenic M2 phenotype induces an increase in oxidative phosphorylation." (PMID 41044469, 2025). "In cancer, IL-1β, IL-4 and IL-6 are well-known for their tumor promoting effects, including enhancing tumor cell proliferation and survival, supporting cancer cell stemness, and facilitating invasion and angiogenesis through autocrine signaling or crosstalk with tumor infiltrating immune cells." (PMID 40108668, 2025). "Moreover, HCC cells co-cultured with M2-derived exosomes released increased amounts of VEGF and IL-4, which in turn led to further recruitment of M2 macrophages and enhanced tumor angiogenesis." (PMID 40264760, 2025). "Delivery of the canonical type 2 inflammatory cytokine, interleukin-4 (IL-4) into the TME could successfully restore tumor control in the presence of IFNα4 in a preclinical ACT model." (PMID 40367186, 2025). "IL4 signaling pathway served as an important role in tumor progression and metastasis." (PMID 39741182, 2025). "However, in this pathology, inducing a Th1-skewed response—characterized by higher IFN-γ production relative to IL-4—is critical for effective anti-tumor immunity." (PMID 39941775, 2025). "Recent work with engineered IL-4 variants suggests that selective modulation of IL-4 signaling could revitalize exhausted CD8+ T cells, providing new opportunities to enhance anti-tumor immunity while minimizing the immunosuppressive effects of the cytokine." (PMID 40864740, 2025).
tumor (continued). "In addition, Th2 CD4+ T-cells impact the tumor immune microenvironment via the secretion of IL-4, IL-5, IL-13, and IL-17, which exert a pro-tumor growth effect." (PMID 40362529, 2025). "Liposomal IL-4, IL-6, and IL-21 therapies show potential across various tumor types." (PMID 40143046, 2025). "Here, bone marrow cells isolated from C57BL/6J mice were differentiated using macrophage colony stimulating factor into macrophages (M0) before polarization toward an M2-like, TCM phenotype by supplementation with interleukin (IL)-4, IL-10, and B16-F10 tumor-conditioned media." (PMID 41050935, 2025). "The janus kinase/signal transducers and activators of transcription signaling pathway plays a pivotal role in the polarization of M2 macrophages, mediated by cytokines such as interleukin-4 (IL-4), IL-6, and interleukin-13 (IL-13), which modulate immune responses and facilitate tumor escape." (PMID 40098971, 2025). "Furthermore, IL-4 facilitates immune evasion by upregulating anti-apoptotic proteins such as Bcl-2 and Bcl-xL, promoting tumor cells’ survival and resistance to apoptosis." (PMID 40864740, 2025). "In both tumor models, IL-4 was down-regulated compared to normal breast tissue." (PMID 39877637, 2025). "IL-15R is a pro-inflammatory cytokine that stimulates NK cell proliferation and expansion, while the IL-4 receptor extracellular domain (ECD) responds to IL-4 in the tumor microenvironment, where inhibitory signals from IL-4R are converted into IL-15R activation signals downstream." (PMID 40612946, 2025). "Nevertheless, the role of IL-4 in enhancing tumor responses raises concerns about whether dupilumab might compromise antitumor efficacy." (PMID 40507326, 2025). "IL-4, for instance, doubles the rate of fusion between human monocytes and tumor cells." (PMID 40507286, 2025). "Notably, MC function is dynamically regulated by tumor micro-environmental signals: IL-1, IL-4, IL-6, and TNF-α activate antitumor effects, whereas VEGF, matrix metalloproteinase, trypsin-like enzymes, and IL-10 promote malignant progression." (PMID 40960294, 2025). "Preclinical data suggest that IL-4 and IL-13 signaling may promote tumor progression by skewing immune responses toward a Th2 phenotype, thereby suppressing anti-tumor Th1 immunity." (PMID 40843371, 2025). "Higher T-helper type 2 (Th2) cytokines (IL-4 and IL-10) in HCC are linked to HCC metastasis and progression, likely due to IL-4-initiated recruitment of TAM, leading to vascular endothelial growth factor (VEGF) and TGF-β secretion, contributing to tumor aggressiveness and metastasis." (PMID 40869156, 2025). "Interestingly, when polarized with IL-4, a component of the immune-suppressive tumor environment, p50−/− macrophage phagocytosis mediated by PSMA.CAR10.3 was ~ fourfold greater than that of PSMA Ab3.9." (PMID 39904797, 2025). "Additionally, IL-4 and IL-5 contribute to enhanced tumor aggressiveness by promoting TAM recruitment and subsequent cytokine secretion." (PMID 40869156, 2025). "Notably, this study also observed a decrease in resting mast cells, which can actively eliminate tumor cells and prevent tumorigenesis through cytokines, such as IL-1, IL-4, IL-6, and TNF-α." (PMID 40755754, 2025). "In the literature, it is known that, in CTCLs, an imbalance towards Th2 polarization driven by IL-4 may contribute to immune evasion and tumor progression by suppressing anti-tumor immune responses and enhancing pro-tumorigenic microenvironments." (PMID 38607023, 2024). "The level of IL-4 (P ═ 0.0048) was significantly correlated with tumor location." (PMID 38920620, 2024). "Comparing IL-4 expression in thymocyte selection-associated HMG BOX (TOX)+ CD4+ T-cells between plaque and tumor lesions, a significant increase in IL-4 and TOX expression was observed in the tumor stage, with a positive correlation between the levels of TOX and IL-4 expression." (PMID 38397043, 2024).
tumor (continued). "However, there is some evidence in the literature to suggest that IL4 signaling acting through CD8 lymphocytes expressing the type I IL4 receptor can boost anti-tumor immunity in the context of immune checkpoint blockade." (PMID 38731867, 2024). "It has been reported that certain cytokines, such as interleukin-4 (IL-4), IL-5, and IL-13, secreted by Th2 cells could stimulate tumor growth." (PMID 38581008, 2024). "The modulation of interleukin-4 and interleukin-13 signaling pathways could be a pivotal mechanism by which epimedium impedes tumor development." (PMID 39011503, 2024). "In summary, IL-4 and IL-13 and their receptors play a significant role in tumor cell biology." (PMID 38519926, 2024). "Immunosuppressive cell types like myeloid-derived suppressor cells (MDSCs), tumor-associated macrophages (TAMs), and regulatory T cells (Tregs) produce anti-inflammatory cytokines, such as interleukin-10 (IL10), IL4, transforming growth factor-beta (TGF-β) that inhibit the CAR T function." (PMID 38962014, 2024). "Moreover, signaling pathways such as SPP1, APRIL (TNFSF13), and IL4 were notably enhanced in the tumor region." (PMID 38938448, 2024). "The enrichment of Th2 cells in HCC may be mediated by STAT5A signaling, facilitating tumor growth or metastasis through immunosuppressive cytokines like IL-4 and IL-10." (PMID 38840234, 2024). "However, the secretion of IL-4 by Th2 cells exacerbates tumor growth by effectively suppressing the host immune system, thus creating a favorable environment for cancer progression." (PMID 39294673, 2024). "This may result from the underexpression of CCL2 and CCR2, responsible for monocyte recruitment to tumor sites, and the reduced levels of IL4 and IL13, genes known to promote monocyte polarization into M2 macrophages." (PMID 38733987, 2024). "Simultaneously, it can also act on myeloid-derived suppressor cells (MDSCs) and promote the secretion of immunosuppressive cytokines such as IL-10 and IL-4, inducing the polarization of Th2 cells, inhibiting anti-tumor immunity, and promoting the occurrence and development of tumors." (PMID 39720595, 2024). "For instance, if the CD4 + T-cell infiltrate is indeed IL-4/IL-13 secreting, this may have functional consequences on the non-tumor cells of the TME." (PMID 38285120, 2024). "In GB, an increase in IL-4 contributes to tumor growth and immune suppression." (PMID 39796096, 2024). "For example, M2 phenotype‐macrophages could secrete IL‐4, IL‐5 and IL‐6 to enhance angiogenesis, immunosuppression and matrix remodelling during tumour progression." (PMID 38680032, 2024). "M2a macrophages promote tumor progression through tumor-released factors and IL-4/IL-13 signaling." (PMID 39796695, 2024). "Importantly, anti-IL-33 monoclonal antibody therapy increase the percentage of CD4+IFNγ+ T cells and decreased CD4+ and CD8+ T cells secreting IL-4 in tumour-draining lymph nodes." (PMID 38662248, 2024). "IL-4 and -13 receptors are up-regulated and activated in many tumours, including OC, which initiates the phosphorylation of Stat6, leading to increased tumour cell proliferation and resistance to apoptosis." (PMID 38974022, 2024). "This statement is supported by an increase in anti-inflammatory cytokines IL-4 and IL-10, both as an evasion of the immune response to tumor cell growth and due to relatively high levels of estrogen and progesterone, which also activate anti-inflammatory cytokines." (PMID 39456554, 2024). "However, M2 macrophages, also called TAMs, are anti-inflammatory cells induced by IL-4 and IL-13 secreted by Th2 cells, which promote cancer cell proliferation, invasion, tumor metastasis, and angiogenesis and participate in immune suppression." (PMID 39605905, 2024). "Therefore, IL-4-STAT6 signaling contributes to POSTN expression in activated CAFs, whereas POSTN-integrin-FAK-STAT3 signaling promotes IL-4 expression in tumor cells during papillary thyroid tumor tumorigenesis." (PMID 38773979, 2024).
tumor (continued). "Additionally, the increased levels of anti-tumor interleukins IL-4, IL-7, IL-28a, and IL-33 in miR-29 overexpressing tumors suggest a role for these microRNAs in bolstering anti-tumor immunity." (PMID 38890285, 2024). "We hypothesize that IL-13 is synergistic with IL-4 in inducing immunotherapy resistance on the one hand, and that it is the result of cytokine storms induced by tumor progression of resistance on the other." (PMID 39003253, 2024). "In the context of the associations with IL-4, IL-9, and TNF-α, high SIGLEC9 expression may have a suppressive effect on the immune system, helping the tumor evade elimination by immune cells." (PMID 39727942, 2024). "Other cytokines, regardless of their proinflammatory (TNFα) or anti-inflammatory effects (IL-4, IL-10), may have diverse effects on promoting tumor growth." (PMID 39000195, 2024). "Furthermore, chronic inflammatory signals in the tumor microenvironment, such as IL-4, can enhance the immunosuppressive functions of TAMs by regulating the metabolism of certain amino acids." (PMID 38185636, 2024). "Tfh cells are the major producers of IL-4 in secondary lymphoid organs, and we confirmed that this was the case in tumor-draining lymph nodes." (PMID 38417020, 2024). "Furthermore, western blot and qRT-PCR assays revealed that FAK inhibitor PF573228 efficiently down-regulated p-STAT3 and IL-4 levels and the STAT3 inhibitor Stattic inhibited the POSTN-induced IL-4 upregulation in tumor cells." (PMID 38773979, 2024). "Mast cells may promote inflammation, inhibition of tumor cell growth, and tumor cell apoptosis by releasing cytokines, such as IL-1, IL-4, IL-6, IL-8, monocyte chemotactic protein-3 and -4 (MCP-3 and MCP-4), TGF-β, and chymase." (PMID 39440039, 2024). "The type 1 immune cytokine IFNγ promotes macrophage polarisation towards the anti-tumour proinflammatory IL-12-producing phenotype, while stimulation by the type 2 cytokines IL-4 and IL-13 results in polarisation towards the tumour-promoting alternatively activated phenotype." (PMID 38745765, 2024). "It was demonstrated that proinflammatory cytokines released by tumor tissue and related inflammatory cells, such as IL-4 and IL-6, could affect the synthesis of albumin in hepatocytes, thus decreasing albumin levels." (PMID 39440062, 2024). "CAFs also indirectly stimulate metastasis through their interactions with TAMs: several CAFs-released cytokines recruit TAMs, such as CCL2 and CCL5 (chemokine ligand 2/5), while IL-4 and IL-6 polarize TAMs toward the M2 phenotype, which supports tumor growth and metastasis." (PMID 39765634, 2024). "However, IL-13, much more than IL-4, plays a critical role in the downregulation of tumor immunosurveillance against several types of tumors." (PMID 39057050, 2024). "Nevertheless, the association between the upregulation of cytokines TGF-β, IL-4/IL-13, IL-10, IL-6, and IL-2 and the overexpression of FAP across multiple tumor types highlights a crucial link between FAP+ CAFs, tumor progression, and evasion of immune surveillance." (PMID 39035007, 2024). "CTSK activates macrophages to secrete IL-4, IL-10, and IL-17, promoting tumor growth and invasion." (PMID 39736788, 2024). "The results showed that IL-4 (P ═ 0.0048) levels were significantly correlated with tumor location." (PMID 38920620, 2024). "Subsequently, these Th2 cells stimulate tumor development by secreting IL-4 and IL-13." (PMID 38557942, 2024). "IL4 plays a crucial role in tumor-promoting survival and growth." (PMID 38672199, 2024). "Furthermore, STAT6D419 mutant tumor cells secrete more of the chemokine CCL17 upon IL-4 stimulation, and we are the first to provide evidence that this leads to increased CD4+ T-cell infiltration in rrDLBCL patient tumor biopsies." (PMID 38285120, 2024). "Thus, this indicates the important role of both IL-6 and IL-4 in stimulating macrophage polarization in the tumor and finally increasing tumor aggressiveness." (PMID 39057050, 2024).
tumor (continued). "Th1 cells suppress malignant tumor proliferation via inducing an immune response to tumors by mainly secreting interferon‐γ (IFN‐γ) and tumor necrosis factor‐α (TNF‐α); while Th2 cells mainly secrete interleukin‐4 (IL4), IL‐10 leading to tumor immunosuppression." (PMID 37096492, 2023). "Meanwhile, the immunosuppressive effects of IL-4 and IL-10 secreted by Th2 cells could further regulate tumor growth and metastasis." (PMID 37181805, 2023). "Together with IL-13, IL-4 may also promote MDSCs to inhibit anti-tumour immunity as shown recently where MDSC-mediated CD8+ T cell suppression is critically dependent on IL-4 and IL-13 signalling." (PMID 37455828, 2023). "Furthermore, APS can upregulate the levels of IL-2 in the serum of 4T1 tumor-bearing mice and H22 hepatoma mice and promote the levels of IL-4 and IL-10 in the serum of tumor-bearing mice treated with a focused ultrasound." (PMID 37959774, 2023). "Many experiments have stated that cytokines are not only released by the immune cells occurring in the tumor microenvironment, but an autocrine source of some inflammatory cytokines (IL-1, IL-4, IL-6 and IL-8) was also confirmed in a large spectrum of solid tumors." (PMID 37763324, 2023). "IL-2 could promote the tumor-specific NK cells and T cells activities, and IL-4 could regulate immune responses." (PMID 37764221, 2023). "In addition, there is evidence that STAT6 can be activated by IL-4 and IL-13 produced by oncogenic Kras driving cells in the tumor microenvironment, and then target cMyc to drive metabolic reprogramming." (PMID 37175092, 2023). "Likewise, an increase in anti-inflammatory cytokines such as IL-4 and IL-10, which are decreased in tumor processes, would presumably occur." (PMID 37960292, 2023). "However, lymph node cells from LY2 tumor-bearing mice stimulated with the IR LY2 tumor cell antigen ex vivo demonstrated increased secretion of IL-4 compared to non-tumor-bearing mice, as determined by cytokine ELISA." (PMID 37444444, 2023). "As revealed by in vitro studies, tumor growth could be directly enhanced by IL-4 and IL-13 through the activation of their receptors on epithelial cells." (PMID 37835465, 2023). "Th2 cells release IL-5, IL-4, and IL-13, resulting in tumor cell growth and metastasis." (PMID 36703939, 2023). "In contrast, IL-4/IL-13 stimulation promotes the M2 phenotype that is characterized by the upregulated expression of arginase 1 (Arg1), which metabolizes L-arginine to various tumor-supporting factors (e.g., L-ornithine and polyamines)." (PMID 37108657, 2023). "In addition, WGP promoted the increase of Th1-type cytokines IFN-γ and IL-2 and the decrease of Th2-type cytokines IL-4 and IL-10, which can induce the differentiation of T cells, further demonstrated its anti-tumor ability." (PMID 36713833, 2023). "Previous studies have reported significant IL-4 expression in the tumor microenvironment." (PMID 38274108, 2023). "In contrast, M2 macrophages, also known as alternatively activated, are polarized by anti-inflammatory molecules Interleukin-4 (IL-4) and Interleukin-13 (IL-13) and are characterized by supporting tumor growth angiogenesis, metastasis, and resistance to chemotherapeutics." (PMID 38116133, 2023). "Pro-inflammatory cytokines such as IL-1β, IL-8, IL-12, TNF-α, IFN-γ, and anti-inflammatory cytokines like IL-4 and IL-10 have dual functions, activating anti-tumorigenic actions of T cells while also participating in tumor malignant transformation, growth, invasion, and metastasis." (PMID 38022654, 2023). "IL-2, IL-15, and IL-21 in the IL-2 cytokine family play a positive role in anti-tumor effects, and IL-4, IL-7 and IL-9 possess pleiotropic functions, with diverse roles in cancer immunity as they can have pro-tumorigenic functions as well as anti-tumorigenic characteristics." (PMID 36936961, 2023). "Following the same rationale as with IL-4, tumor cells have been engineered to secrete IL-13." (PMID 36980536, 2023).